RAB22A (RAB22A, member RAS oncogene family)
Diseases named in the same sentence as RAB22A in open-access papers (continued):
Sharing a sentence is not in itself a finding about the gene and the disease.
melanoma (12 papers, 2010 to 2025). A malignant, usually aggressive tumor composed of atypical, neoplastic melanocytes. "DNMT1 regulated the DNA methylation in the promoter region of miR-211, decreased the expression level of miR-211 in melanoma cells and increased the expression level of its downstream target gene RAB22A, thus promoting the EMT process." (PMID 38431306, 2024). "Previous studies have found that RAB22A participates in EMT process in melanoma and colorectal cancer, leading to malignant development of tumor." (PMID 38431306, 2024). "According to previous studies, RAB22A has been uncovered, as a member of oncogene family, to promote melanoma growth and renal cell carcinoma development." (PMID 34592939, 2021). "Although RAB22A has recently been reported to be upregulated in hepatocellular carcinoma, cholangiohepatoma, melanoma and colorectal cancer, little is known about its role in human tumorigenesis, especially in human glioma." (PMID 26134825, 2015). "Previous reports indicated that the expression of Rab22a is increased in different cancer types, including liver cancer and malignant melanoma, suggesting an oncogenic role for Rab22a." (PMID 25460499, 2014). "RAB22A was found to reside in regions of chromosomal breakpoints and has altered/increased expression in melanoma." (PMID 20302635, 2010). "Therefore, the DNMT1/miR‐211/RAB22A axis offers a fresh perspective on the aetiology of melanoma, specifically concerning its involvement in the EMT pathway." (PMID 40387409, 2025). "However, RAB22A plays important roles in multiple cancers containing liver cancer, ovarian cancer, malignant melanoma and CCA, and participates in multiple cell signaling pathways." (PMID 34012964, 2021). "Also, the expression of RAB22A determines the progression of multiple tumors, including liver cancer, ovarian cancer and malignant melanoma." (PMID 34012964, 2021). "Similarly, RAB22A expression is also a prognostic factor of poor outcome in melanoma patients, showing an increased expression in primary melanomas compared with benign nevi." (PMID 33072757, 2020). "Furthermore, miR‐211 functions as a tumour suppressor in melanoma by negatively regulating RAB22A." (PMID 40387409, 2025). "Thus, the EZH2/DNMT1/MIR211/RAB22A axis might provide novel insights into the molecular pathogenesis of both melanoma and glioblastoma, particularly on the EMT processes in these two different cancers." (PMID 33628737, 2020). "In melanoma cells, MIR211 can modulate EMT by targeting RAB22A, a member of the RAB family of small GTPase, which regulates tumor invasion and metastasis in various cancer types." (PMID 33628737, 2020).
ovarian carcinoma (9 papers, 2014 to 2024). A malignant neoplasm originating from the surface ovarian epithelium. "The down-regulation of Rab22a was strongly correlated with the over-expression of miR-373 in xenograft ovarian carcinoma metastatic models in nude mice by SKOV3luc-pMSCV-miR-373 cells." (PMID 25460499, 2014). "Moreover, Rab22a overexpression abrogates the miR-373 effects on suppressing cell invasion and migration in epithelial ovarian cancer cells." (PMID 38695990, 2024). "Additionally, knockdown of Rab22a inhibits invasion and migration of epithelial ovarian cancer cells, increases E-cadherin expression but suppresses N-cadherin expression." (PMID 38695990, 2024). "Additionally, a recent study showed that HOTAIR controls Rab22a expression in ovarian cancer by sponging miR-373 and regulates HER2 expression in gastric cancer by sponging miR-331-3p." (PMID 33302562, 2020). "Transient expression of miR-373 and siRNA-based knockdown of Rab22a showed essentially similar effects in ovarian cancer cells, further confirming that direct targeting of Rab22a by miR-337 plays an important inhibitory role in migration and invasion of ovarian cancer cells." (PMID 25460499, 2014). "We show for the first time that the miR-373/Rab22a axis contributes to migration and invasion in ovarian cancer and may represent a potential therapeutic target for the disease." (PMID 25460499, 2014).
colorectal cancer (8 papers, 2015 to 2025). A primary or metastatic malignant neoplasm that affects the colon or rectum. "MCF2L-AS1 promoted the EMT of colorectal cancer by targeting the miR-105-5p/RAB22A axis, thus making the malignant progression of colorectal cancer." (PMID 38431306, 2024). "MiR-204-5p exerts a potent tumor suppressor function in colorectal cancer by repressing RAB22A (a member of the RAS oncogene family)." (PMID 36568397, 2022). "For example, miR-204 targets RAB22A to inhibit the proliferation and invasion of colorectal cancer cells." (PMID 30981205, 2019). "In a previous report, Rab22a, a member of the RAS oncogene family and one of the endosome-associated proteins, was experimentally validated as a target of miR-204 using colorectal cancer cells." (PMID 30042818, 2018).
gastric cancer (6 papers, 2017 to 2021). A primary or metastatic malignant neoplasm involving the stomach. "RAB22A has been shown to act as a direct functional target of miR-204-5p, the levels of which are regulated by miR-204-5p in several cancers, such as gastric cancer and glioma." (PMID 34783622, 2021). "Furthermore, another study indicated that miR-204-5p suppressed gastric cancer cell growth by inhibiting RAB22A and USP47." (PMID 33888645, 2021). "Getting together, in miR-204 regulation pathway, USP47, RAB22A, SIRT1, Snai1, and so forth and SOX4 may play an associating role contributing to gastric cancer progressing." (PMID 28133610, 2017). "Previous studies showed that miR-204 suppressed gastric cancer through targeting USP47, RAB22A, SIRT1, Snai1, and so forth." (PMID 28133610, 2017). "USP47, RAB22A, SIRT1, Snai1, and so forth are targets of miR-204 that mediate miR-204 reducing the oncogenicity of gastric cancer." (PMID 28133610, 2017).
glioma (5 papers, 2015 to 2023). A benign or malignant brain and spinal cord tumor that arises from glial cells (astrocytes, oligodendrocytes, ependymal cells). "Several tumor models, including kidney, colorectal, glioma, and bile duct cancer, have utilized RAB22A as a target gene for miRNAs." (PMID 36936971, 2023). "Low expression levels of miR-204-5p glioma contained comparatively high RAB22A expression than those in high miR-204-5p expression specimens." (PMID 26134825, 2015). "Taken together, these results imply that miR-204-5p exerts tumor-suppressive function in glioma cells via directly targeting RAB22A." (PMID 26134825, 2015). "Overexpression of miR-204-5p is able to suppress glioma cell growth and metastasis through directly targeting RAB22A." (PMID 26134825, 2015). "Western blot analysis also demonstrated that siRAB22A was able to effectively knockdown the expression of RAB22A in glioma LN229 and U87 cells." (PMID 26134825, 2015). "In the subsequent mechanistic study, we demonstrated that miR-204-5p directly targets RAB22A to inhibit proliferation, migration and invasion in glioma cells." (PMID 26134825, 2015). "The detailed role and mechanism by which RAB22A promotes glioma development and progression should be investigated in future work." (PMID 26134825, 2015). "Downregulation of miR-204-5p in human gliomas is correlated with poor patient prognosis, and overexpression of miR-204-5p inhibits the proliferation, migration and invasiveness of glioma cells in vitro and in vivo by directly targeting RAB22A (a member of the RAS oncogene family)." (PMID 28435518, 2017). "Further mechanistic investigations revealed that miR-204-5p inhibits gliomas cell growth, migration and invasion by directly targeting RAB22A (a member of the RAS oncogene family), which appears to be a new prognostic factor in gliomas." (PMID 26134825, 2015). "Furthermore, mechanistic investigations revealed that RAB22A, a member of the RAS oncogene family, is a direct functional target of miR-204-5p in gliomas." (PMID 26134825, 2015).
hepatocellular carcinoma (5 papers, 2015 to 2024). A malignant tumor that arises from hepatocytes. "In another study, RAB22A was significantly up-regulated in hepatocellular carcinoma, which was significantly related to the infiltration of various immune cells and the gene expression of immune checkpoints, and may lead to poor prognosis of hepatocellular carcinoma by regulating immune function." (PMID 38431306, 2024).
liver cancer (4 papers, 2014 to 2023). An epithelial or non-epithelial malignant neoplasm that arises from the liver. "The high expression of RAB22A in stage M0 liver cancer was associated with poor OS, DSS, and PFI in a subgroup of patients." (PMID 36936971, 2023). "Overexpression of Rab22a has been observed previously in liver cancer and MM cell lines, suggesting an oncogenic role for Rab22a in tumorigenesis." (PMID 25460499, 2014).
lung carcinoma (4 papers, 2019 to 2022). "By enhancing the recycling of CD147, Rab22a promotes the invasion and migration of lung cancer cells." (PMID 35757470, 2022). "Among the many predicted targets, seven genes (SOX4, ZEB2, AVL9, PTPN9, RAB22A, ITGB8 and SIX1) that have been reported to play an oncogenic role in lung cancer were further analyzed." (PMID 35287543, 2022). "In 2017, a study reported that Rab22a could enhance CD147 recycling and was required for the migration and invasion of lung cancer cells." (PMID 34012964, 2021).
renal cell carcinoma (4 papers, 2019 to 2022). "MiR-204, on the other hand plays tumor suppressive role by targeting CDC42 and RAB22A in nasopharyngeal and renal cell carcinoma respectively." (PMID 33790326, 2021).
atherosclerosis (3 papers, 2022 to 2024). A disease characterized by the build-up of fatty material and calcium deposition in the arterial wall resulting in partial or complete occlusion of the arterial lumen. "miR-654-3p was found to reduce inflammation by targeting ADAM10 and RAB22A (both promoters of atherosclerosis) and TNFRSF9 (TNF receptor family member 9)." (PMID 39201485, 2024). "m6A modifications of the lncRNA ZNFX1 Antisense RNA 1 (ZFAS1) and RAB22A, member RAS oncogene family (RAB22A) via METTL14 contributes to the development of atherosclerosis." (PMID 36482889, 2022).
clear cell renal cell carcinoma (3 papers, 2021 to 2025). "Professor Liu confirmed that LINC01232 promotes clear cell renal cell carcinoma by binding miR-204-5p to upregulate RAB22A." (PMID 35910212, 2022).
nasopharyngeal carcinoma (3 papers, 2020 to 2025). A carcinoma arising from the nasopharyngeal epithelium. "The tumor suppressive actions and chemotherapy sensitivity enhancement activity of miR-204, via the inhibition of RAB22A, an oncogene, has been investigated for multiple cancers including nasopharyngeal carcinoma." (PMID 40176914, 2025). "Consistently, RAB22A enhances the antitumor effect of the STING agonist diABZI in mice, and a high RAB22A level predicts good survival in nasopharyngeal cancer patients treated with chemoradiotherapy." (PMID 36280710, 2022).
papillary thyroid cancer (2 papers, 2022 to 2023). "RAB22A promotes the epithelial–mesenchymal transition of papillary thyroid cancer cells, thereby promoting their proliferation, migration, and invasion." (PMID 36936971, 2023). "The proliferation, migration, invasion, and EMT in papillary thyroid carcinoma cell lines were enhanced upon Rab22a overexpression but inhibited after knocking down Rab22a." (PMID 35757470, 2022). "In papillary thyroid carcinoma, thyroid follicular carcinoma, and medullary thyroid carcinoma, Rab22a was positively overexpressed in tumor tissues and negatively expressed in adjacent normal thyroid tissues or nodular goiters." (PMID 35757470, 2022). "Rab22a can promote the EMT process and enhance proliferation, migration, and invasion of papillary thyroid carcinoma cells by activating the PI3K/AKT/mTOR signaling pathway." (PMID 35757470, 2022). "To further explore the correlation between Rab22a and thyroid tumors, we conducted a series of in vitro experiments in thyroid papillary carcinoma cell lines, TPC1, and K1, to detect the effect influence of Rab22a on malignant behavior of cells." (PMID 35757470, 2022). "By bi-bidirectionally manipulating the expression of Rab22a, its function in proliferation, migration, invasion, and epithelial-mesenchymal transition (EMT) was investigated in papillary thyroid carcinoma cells." (PMID 35757470, 2022). "However, the ability of Rab22a to promote the proliferation, invasion, migration, and EMT of papillary thyroid carcinoma cells was significantly inhibited after being treated with LY294002, a PI3K inhibitor." (PMID 35757470, 2022).
viral diseases (2 papers, 2022 to 2026). "Virus infection-elicited downregulation of RBM25 results in Rab22a upregulation, which consequently potentiates viral entry." (PMID 42299815, 2026). "Moreover, some genes related to protein secretion and reactive oxygen species pathways like MAPK1, RAB14, RAB22A, SOD1, and CAT were dysregulated in COVID-19 versus other-viral diseases." (PMID 35922752, 2022).
benign ovarian tumor (1 paper, 2014). "IHC analysis was used to measure the expression of Rab22a protein in 30 cases of EOC tissue, 15 cases of benign ovarian tumor tissues and 10 cases of normal ovarian tissues." (PMID 25460499, 2014).
gallbladder cancer (1 paper, 2022). "Rab22a is a direct downstream target of miR-520b, upregulated in gallbladder cancer, and negatively correlated with miR-520b expression." (PMID 35757470, 2022). "When the expression of Rab22a was inhibited, the proliferation, invasion, and migration ability of gallbladder cancer cells were significantly inhibited." (PMID 35757470, 2022).
lung adenocarcinoma (1 paper, 2024). A carcinoma that arises from the lung and is characterized by the presence of malignant glandular epithelial cells. "Moreover, Rapamycin, the mTOR inhibitor, is proved to effectively suppress Rab22a-triggered proliferation, migration and invasion in lung adenocarcinoma cells, indicating that Rab22a regulates the biological malignancies of lung adenocarcinoma cells through activating PI3K/AKT/mTOR signaling." (PMID 38695990, 2024).
medulloblastoma (1 paper, 2019). A malignant, invasive embryonal neoplasm arising from the cerebellum. "Known validated targets of miR-204 like RAB22A, M6PR are at the top of the list whose downregulation upon miR-204 expression was further confirmed by real time RT-PCR in the three medulloblastoma cell lines." (PMID 30944042, 2019). "Transcriptome sequencing / real time RT-PCR / western blot analysis showed downregulation of RAB22A, M6PR, EZR, EPHB2, upon miR-204 expression in medulloblastoma cells as well." (PMID 30944042, 2019).
nodular goiter (1 paper, 2022). Goiter characterized by discrete tissue mass(es) that may or may not produce thyroid hormones. "In this study, we compared the expression of Rab22a in thyroid cancer tissues and nodular goiters." (PMID 35757470, 2022). "Immunostaining showed that Rab22a was significantly overexpressed in thyroid cancer tissues but negative in adjacent normal tissues or nodular goiters." (PMID 35757470, 2022).
thyroid cancer (1 paper, 2022). "Altogether, these results suggest that Rab22a can enhance the malignant biological behavior of thyroid cancer cells by activating the PI3K/AKT/mTOR signaling pathway." (PMID 35757470, 2022). "By upregulating and downregulating the expression of Rab22a in thyroid cancer cell lines, the effect of Rab22a on cell proliferation, invasion, and migration was analyzed." (PMID 35757470, 2022). "Statistical analysis of the expression of Rab22a and related clinicopathological parameters revealed that the expression of Rab22a in benign thyroid tissues and malignant thyroid tumors has significant differences." (PMID 35757470, 2022). "Taken together, these results suggested that, in thyroid cancer cells, Rab22a may promote EMT through upregulating PI3K/AKT/mTOR signaling pathway." (PMID 35757470, 2022). "In summary, the thyroid cancer tissues showed specific overexpression of Rab22a." (PMID 35757470, 2022). "In the current study, we found that the expression of Rab22a was upregulated in thyroid cancer." (PMID 35757470, 2022). "The current study further explored the relationship between Rab22a and PI3K/AKT/mTOR signaling pathway to verify the influence of Rab22a on the malignant progression of thyroid cancer cells, which was unprecedented." (PMID 35757470, 2022). "The overexpressed Rab22a can activate the PI3K/AKT/mTOR signaling pathway, thereby promoting EMT of thyroid cancer cells and enhancing the proliferation, migration, and invasion of thyroid cancer cells." (PMID 35757470, 2022). "However, the relationship between Rab22a and the PI3K/AKT/mTOR signaling pathway in thyroid cancer has never been explored." (PMID 35757470, 2022).
thyroid tumor (1 paper, 2022). A benign or malignant neoplasm affecting the thyroid gland. "We found that the expression of RAB22A in thyroid tumor tissues was higher than that in normal tissues." (PMID 35757470, 2022). "In addition, database analysis shows that the expression of RAB22A in different stages of thyroid tumors has no obvious difference (GEPIA (cancer-pku.cn))." (PMID 35757470, 2022).